CSF1 (colony stimulating factor 1)
Description:
Cytokine that plays an essential role in the regulation of survival, proliferation and differentiation of hematopoietic precursor cells, especially mononuclear phagocytes, such as macrophages and monocytes. Promotes the release of pro-inflammatory chemokines, and thereby plays an important role in innate immunity and in inflammatory processes. Plays an important role in the regulation of osteoclast proliferation and differentiation, the regulation of bone resorption, and is required for normal bone development. Required for normal male and female fertility. Promotes reorganization of the actin cytoskeleton, regulates formation of membrane ruffles, cell adhesion and cell migration. Plays a role in lipoprotein clearance.
Synonyms: CSF-1; M-CSF; MCSF; PG-M-CSF; MGC31930
Tractability: Antibody: a drug acting on it is in phase 2 or 3 trials; UniProt places it where antibodies can reach, with high confidence; its Gene Ontology location is reachable by antibodies, with high confidence; UniProt predicts a signal peptide or a membrane-spanning region; the Human Protein Atlas places it where antibodies can reach.
Target class: Secreted protein
Gene: Protein-coding gene on chromosome 1 (109,910,242 to 109,930,993, forward strand). Ensembl gene ENSG00000184371.
Subcellular location: Cell membrane; Secreted, extracellular space (Processed macrophage colony-stimulating factor 1)
Subcellular location (Human Protein Atlas): Plasma membrane; Nuclear bodies; Predicted to be secreted
Pathways (Reactome):
Immune System: Interleukin-10 signaling; Other interleukin signaling; Signaling by CSF1 (M-CSF) in myeloid cells
Metabolism of proteins: Post-translational protein phosphorylation; Regulation of Insulin-like Growth Factor (IGF) transport and uptake by Insulin-like Growth Factor Binding Proteins (IGFBPs)
Developmental Biology: Transcriptional and post-translational regulation of MITF-M expression and activity
Gene Ontology:
Molecular function: cytokine activity; growth factor activity; identical protein binding; protein binding; protein homodimerization activity; macrophage colony-stimulating factor receptor binding
Biological process: cell surface receptor protein tyrosine kinase signaling pathway; osteoclast differentiation; positive regulation of cell population proliferation; positive regulation of gene expression; positive regulation of macrophage chemotaxis; positive regulation of macrophage colony-stimulating factor signaling pathway; positive regulation of macrophage derived foam cell differentiation; positive regulation of macrophage differentiation; positive regulation of macrophage migration; positive regulation of microglial cell migration; positive regulation of mononuclear cell proliferation; positive regulation of osteoclast differentiation; positive regulation of protein metabolic process; response to ischemia; developmental process involved in reproduction; innate immune response; macrophage differentiation; monocyte activation; positive regulation of cell migration; positive regulation of cell-matrix adhesion; positive regulation of monocyte differentiation; regulation of macrophage derived foam cell differentiation; macrophage colony-stimulating factor signaling pathway; microglial cell proliferation; positive regulation of immune system process
Cellular component: CSF1-CSF1R complex; extracellular region; perinuclear region of cytoplasm; plasma membrane; receptor complex; endoplasmic reticulum lumen; membrane
Genetic constraint (gnomAD): Loss-of-function variants: 9 observed, 46.49 expected, observed/expected ratio (o/e) 0.19, 90% interval 0.12 to 0.34. The upper end of that interval is the gene's LOEUF score, 0.34, which puts it in group 1 of 6, group 1 being the genes least tolerant of losing a copy. Missense variants: 672 observed, 707.89 expected, observed/expected ratio (o/e) 0.95, 90% interval 0.89 to 1.01. Synonymous variants: 305 observed, 288.74 expected, observed/expected ratio (o/e) 1.06, 90% interval 0.96 to 1.16.
Homologues: Orthologues: chimpanzee CSF1 (97% identical), macaque CSF1 (96% identical), pig CSF1 (75% identical), dog CSF1 (75% identical), mouse Csf1 (70% identical), rabbit CSF1 (66% identical), rat Csf1 (64% identical), zebrafish csf1a (14% identical), zebrafish csf1b (10% identical).
Diseases named in the same sentence as CSF1 in open-access papers:
CSF1 is named in the same sentence as 458 diseases in open-access papers, as found by Europe PMC text mining. Sharing a sentence is not in itself a finding about the gene and the disease. The quoted sentences say what the papers report.
breast cancer (259 papers, 2006 to 2026). A primary or metastatic malignant neoplasm involving the breast. "In recent years, studies on RNA modifications in both ovarian and breast cancer have revealed that Macrophage Colony Stimulating Factor 1(CSF-1) is associated with unfavorable prognoses in both cases." (PMID 38291517, 2024). "The expression of csf1r gene, which produces CSF1R and CSF1, is strongly associated with poor outcome in breast cancer and results in tumor cell invasiveness and pro-metastatic behavior both in patient and in vitro." (PMID 38822100, 2024). "The colony stimulating factor 1 (CSF-1), a critical regulator of macrophages, is linked with a poor prognosis in breast cancer patients." (PMID 39507526, 2024). "CSF-1 and its receptor (CSF-1R) assist in the regulation of macrophages; CSF-1R and/or CSF-1 expressions are potentially associated with a poor breast cancer prognosis." (PMID 39309874, 2024). "CSF1 encodes macrophage colony-stimulating factor 1, a cytokine that controls immune responses and promotes breast cancer progression." (PMID 38028209, 2023). "In breast cancer, CSF1 stimulates tumor-associated macrophages (TAMs) that contribute to tumor initiation and progression by promoting angiogenesis, extracellular matrix breakdown, and tumor cell motility." (PMID 35406623, 2022). "IL4 signaling in macrophages also transcriptionally regulated other genes causally associated with mammary cancer lung metastasis, including Ccl2, Csf1, Ccr1, Hgf and Flt1." (PMID 36077870, 2022). "CSF-1 expression is associated with poor prognosis and increased infiltration of CSF-1 receptor (CSF-1R)-expressing macrophages in mouse models of breast cancer." (PMID 33968034, 2021). "Numerous studies have reported that high expression of CSF-1 or its receptor CSF-1R is associated with poor prognosis in malignant tumors, such as in breast cancer and Hodgkin’s lymphoma." (PMID 34178692, 2021). "In patients with breast cancer, upregulation of CSF-1 and CSF-1 receptor (CSF-1R) is associated with inferior prognosis." (PMID 34359674, 2021). "The Csf1- gene, implicated in the proliferation, differentiation, and recruitment of macrophages in breast cancer, was unchanged." (PMID 33297495, 2020). "In a mouse model of breast cancer, defects of CSF-1 caused delays in the development of metastatic tumors." (PMID 31963413, 2020). "A high level of CSF-1 or CSF-1R expression in the tumour or peri-tumoral tissue has been associated with poor patient survival in different malignancies such as lymphoma, breast cancer and hepatocellular carcinoma." (PMID 31331034, 2019). "CSF1 recruits macrophages, and a “CSF response signature” was seen in a subset of breast cancer that was associated with higher grade and decreased estrogen receptor expression." (PMID 30999901, 2019). "Overexpression of CSF-1 has been associated with several human cancers, including breast cancers, renal cell carcinomas, and ovarian cancers." (PMID 31565097, 2019). "A previous study of breast cancer defined a 112-gene CSF1 response signature associated with higher tumor grade, decreased expression of estrogen receptor (ER) and progesterone receptor (PR), and higher mutation rate." (PMID 30930117, 2019). "In conclusion, our study shows that the mRNA expression pattern of IL-34 was distinct from CSF-1 and associated with a favorable prognosis dependent on the molecular breast cancer subtype." (PMID 29796177, 2018). "To explore their potential biological role, we studied the association between IL-34, CSF-1 and their receptors with immune cell infiltration based on the breast cancer dataset of The Cancer Genome Atlas (TCGA)." (PMID 29796177, 2018). "Macrophage-deficient female CSF-1-deficient mice, when crossed with the mammary tumor-prone Polyoma middle T antigen (PyMT) mouse, rarely develop pulmonary metastases, despite the formation of large numbers of primary mammary epithelial tumors." (PMID 28629162, 2017).
breast cancer (continued). "In an animal model, lung metastasis of mammary tumors was delayed in transgenic mice harboring a recessive null mutation in the CSF-1 gene, while transgenic expression of CSF-1 accelerated the progression and metastasis of mammary gland tumors." (PMID 25884955, 2015). "In this model, genetically deleting colony stimulating factor-1 (CSF-1), a key chemoattractant of macrophages, makes PyMT mice susceptible to mammary cancer." (PMID 23673510, 2013). "FOTS-/TGCT/CSF1- breast cancers were associated with better outcome in OS, DSS and DFS, while FOTS+/TGCT/CSF1- breast cancers were associated with worse outcome in OS, DSS and DFS." (PMID 24342436, 2013). "Previously, our group reported that the DTF fibroblast signature is associated with good outcome in breast cancer, and that the TGCT/CSF1 macrophage signature is associated with higher tumor grade in breast cancer." (PMID 24342436, 2013). "In IL-1 receptor-deficient or CSF-1-deficient mice in which tumor microenvironment was markedly altered by reduced infiltration of leukocytes, spontaneous lung metastasis of breast cancer cells was significantly reduced." (PMID 23527025, 2013). "Studies of the effects of CSF-1 on tumour progression and establishment of metastasis showed that mice deficient in macrophage CSF-1 had delayed metastatic spread of mammary tumours to the lungs." (PMID 22005011, 2011). "For instance, the genetic ablation of the Csf1 gene (which encodes M-CSF and is required in macrophage maturation) could lead to the delayed metastasis of mammary carcinoma, whereas the transgenic expression of the M-CSF could speed up pulmonary metastasis." (PMID 37509382, 2023). "Furthermore, IL4 signaling in macrophages regulated the transcript abundance of several other genes already causally associated with mammary cancer lung metastasis including Ccl2, Csf1, Ccr1, Hgf and Flt1." (PMID 36077870, 2022). "Notably, CSF1 is implicated in the progression of breast cancer, is overexpressed in triple-negative breast cancer (TNBC) cell lines, and its enhancer is primarily active in TNBC patient tumors." (PMID 35406623, 2022). "In our study, we identified a 37-gene TAM signature that is highly expressed in the most aggressive breast cancer subtypes and enriched in a CSF1-high group that has been previously associated with higher tumor grade, decreased expression of ER and PR, and higher mutation rate." (PMID 30930117, 2019). "The finding that high levels of IL-34 are associated with better prognosis in certain breast cancer subtypes is surprising, since the expression of CSF-1 and the common receptor CSF-1R has been linked to aggressive behavior and poor prognosis in breast cancer patients." (PMID 29796177, 2018). "For instance, when a null mutation colony stimulating factor-1 gene was crossed into transgenic mice susceptible to mammary cancer due to the expression of the polyoma middle T antigen oncogene (PyMT mice), depletion of macrophages resulted in delayed tumor progression and tumor metastasis." (PMID 21747968, 2011). "For instance, colony-stimulating factor-1 (CSF-1) can promote the malignant transformation of breast cancer by attracting macrophages." (PMID 40933995, 2025). "Although there remains interest in agents targeting CSF-1, hepatic toxicity appears to be a limiting factor for their use in early breast cancer." (PMID 39625569, 2025). "Specifically, CSF-1 stimulates the survival, proliferation, and differentiation of monocytes and promotes the proliferation and motility of macrophages in breast cancer." (PMID 40940867, 2025). "Co-culturing a different breast cancer cell line, 4T1, which also secretes CSF-1, with BAC1.2F5 macrophages also caused an increase in VEGF-A secretion by macrophages." (PMID 40646332, 2025). "Breast cancer cells secrete colony-stimulating factor 1 (CSF1) to induce the monocytic expression and secretion of CXC motif chemokine ligand 7 (CXCL7) in the TME." (PMID 40243781, 2025).
breast cancer (continued). "CSF-1/CSF-1R inhibitors have been identified as therapeutic targets for a variety of malignant tumors, such as glioma, hepatocellular carcinoma, breast cancer, lung cancer and pancreatic cancer, and have broad application prospects in tumor immunotherapy." (PMID 40007537, 2025). "Administration of CSF-1 antisense oligodeoxyribonucleotide and siRNA directed against CSF-1 mRNA or host (mouse) CSF-1 receptors to mice bearing human breast cancer xenografts suppressed tumor growth by 40–50% and increased mouse survival." (PMID 39941714, 2025). "TGF-β and Colony Stimulating Factor 1 (CSF-1) present in breast cancer trigger epigenetic modulation of the TAM phenotype to promote tumor growth." (PMID 41154396, 2025). "Colony-stimulating factor 1 (CSF-1) facilitates the recruitment of TAMs into the TME of breast cancer, where they promote tumor invasion and metastasis." (PMID 41142826, 2025). "In the tumor-bearing model of breast cancer, combination of CSF-1 monoclonal antibody or PLX3397 would lead to depletion of immunosuppressed macrophages, significantly delaying tumor regeneration after radiotherapy." (PMID 40007537, 2025). "In summary, the overexpression of ALKBH3 in ovarian and breast cancer leads to a reduction in m1A levels within CSF-1 mRNA." (PMID 38291517, 2024). "Human breast cancer cell lines and animal models illustrate that breast tumor cells can produce colony-stimulating factor (CSF)-1 (macrophage [M]-CSF) and CCL2, which are considered the most significant attractants and growth factors for TAMs." (PMID 39309874, 2024). "Chemokine (C-C motif) ligand 5(CCL5) and CCR5 signaling regulates the expression of CSF1 in breast cancer cells, while CSF1 and CSF1 receptor (CSF1R) signaling regulates the expression of CCL5 in mesenchymal stem cells." (PMID 39192979, 2024). "Inhibiting CSF1 to deplete macrophages within tumors significantly diminishes the angiogenic potential of breast cancer and tumor burden, but restoring the expression levels of CSF1 can block TAM depletion and enhance the angiogenic potential of tumors." (PMID 39691707, 2024). "rs2373011 is located in the intron region of the ANKS1B gene, whereas rs2229165 of the CSF1 gene has also been suggested to be involved in breast cancer etiology." (PMID 39194753, 2024). "Previous work demonstrated CSF-1R expression at the membrane and in the nucleus of CSF-1-stimulated cervical, ovarian and breast cancer cell lines." (PMID 38254773, 2024). "In a paclitaxel-treated mouse model of breast cancer, tumor cells upregulated the expression of colony-stimulating factor 1 (CSF-1) and resulted in the recruitment of TAMs and resistance to paclitaxel." (PMID 38787372, 2024). "In a mouse model of breast cancer (PyMT), the depletion of intratumoral macrophages (colony stimulating factor 1 (CSF-1) null mutant mice) or the conditional knock-out of their secreted VEGF led to a delay of the angiogenic switch of the tumor vasculature." (PMID 37234993, 2023). "For example, colony stimulating factor-1 (CSF-1) promotes malignant transformation in mammary cancer by recruiting macrophages." (PMID 36845095, 2023). "Blockage of CSF1 expression by siRNA in the breast cancer in vivo model inhibited tumor growth and reduced the recruitment of macrophages to TME." (PMID 37736898, 2023). "Fascinatingly, CSF1 and EGF establish a feedback paracrine loop between CSCs and TAMs, where CSF1 recruited TAMs shed a higher amount of EGF leading to stimulation of STAT3/SOX2 pathway in breast cancer cells." (PMID 38035101, 2023). "In breast cancer, miR-149 acts as a metastasis-repressing microRNA by limiting the colony-stimulating factor-1 (CSF1)-dependent mobilization of macrophages as well as M2 macrophage polarization." (PMID 37744277, 2023). "By modulating SRC-1 expression, c-MYC activates colony-stimulating factor 1 (CSF-1) and enriches macrophages to enhance breast cancer metastasis." (PMID 36721232, 2023).